IL20 (interleukin 20)
Description:
Pro-inflammatory and angiogenic cytokine mainly secreted by monocytes and skin keratinocytes that plays crucial roles in immune responses, regulation of inflammatory responses, hemopoiesis, as well as epidermal cell and keratinocyte differentiation. Enhances tissue remodeling and wound-healing activities and restores the homeostasis of epithelial layers during infection and inflammatory responses to maintain tissue integrity. Affects multiple actin-mediated functions in activated neutrophils leading to inhibition of phagocytosis, granule exocytosis, and migration. Exert its effects via the type I IL-20 receptor complex consisting of IL20RA and IL20RB. Alternatively, can mediate its activity through a second receptor complex called type II IL-20 receptor complex composed of IL22RA1 and IL20RB. Acts as an arteriogenic and vascular remodeling factory by activating a range of signaling processes including phosphorylations of JAK2 and STAT5 as well as activation of the serine and threonine kinases AKT and ERK1/2 (By similarity). Alternatively, can activate STAT3 phosphorylation and transcriptional activity in a JAK2, ERK1/2 and p38 MAPK-dependent manner in keratinocytes.
Synonyms: IL-20; ZCYTO10; IL10D
Tractability: Antibody: a drug acting on it is in phase 2 or 3 trials; UniProt places it where antibodies can reach, with high confidence; its Gene Ontology location is reachable by antibodies, with high confidence; UniProt predicts a signal peptide or a membrane-spanning region.
Target class: Secreted protein
Gene: Protein-coding gene on chromosome 1 (206,865,623 to 206,869,223, forward strand). Ensembl gene ENSG00000162891.
Subcellular location: Secreted
Subcellular location (Human Protein Atlas): Vesicles; Endoplasmic reticulum; Predicted to be secreted
Pathways (Reactome):
Immune System: Interleukin-20 family signaling
Gene Ontology:
Molecular function: cytokine activity; interleukin-20 receptor binding; interleukin-22 receptor binding; signaling receptor binding
Biological process: cytokine-mediated signaling pathway; dendritic cell differentiation; immune response; osteoclast differentiation; positive regulation of epidermal cell differentiation; positive regulation of keratinocyte differentiation; positive regulation of tyrosine phosphorylation of STAT protein; regulation of inflammatory response
Cellular component: extracellular region; interleukin-20 receptor complex
Genetic constraint (gnomAD): Loss-of-function variants: 16 observed, 17.11 expected, observed/expected ratio (o/e) 0.94, 90% interval 0.63 to 1.42. The upper end of that interval is the gene's LOEUF score, 1.42, which puts it in group 5 of 6, group 1 being the genes least tolerant of losing a copy. Missense variants: 176 observed, 193.95 expected, observed/expected ratio (o/e) 0.91, 90% interval 0.8 to 1.03. Synonymous variants: 64 observed, 71.1 expected, observed/expected ratio (o/e) 0.9, 90% interval 0.74 to 1.11.
Homologues: Orthologues: chimpanzee IL20 (100% identical), macaque IL20 (98% identical), dog IL20 (86% identical), pig IL20 (81% identical), guinea pig IL20 (78% identical), mouse Il20 (75% identical), rabbit IL20 (75% identical), rat Il20 (74% identical), zebrafish il19l (36% identical). Paralogues in human: IL19 (41% identical), IL24 (31% identical), IL10 (26% identical), IL26 (19% identical).
Diseases named in the same sentence as IL20 in open-access papers:
IL20 is named in the same sentence as 151 diseases in open-access papers, as found by Europe PMC text mining. Sharing a sentence is not in itself a finding about the gene and the disease. The quoted sentences say what the papers report.
psoriasis (76 papers, 2006 to 2026). An autoimmune condition characterized by red, well-delineated plaques with silvery scales that are usually on the extensor surfaces and scalp. "Aberrant IL-20 expression has been implicated in numerous inflammatory diseases, including psoriasis." (PMID 37887308, 2023). "IL‐19 and IL‐20, members of the IL‐10 family, were found to be associated with psoriasis‐like skin abnormalities and upregulate psoriasis‐related cytokines." (PMID 36245291, 2022). "IL-20 cytokines are associated with many inflammatory diseases, such as psoriasis, rheumatoid arthritis, COPD or infectious diseases." (PMID 34944654, 2021). "The IL-20 gene is located in chromosome 1 and two polymorphisms (rs1400986 and rs1518108) have been associated with inflammatory diseases, such as, psoriasis and ulcerative colitis." (PMID 31947776, 2020). "Recent studies reported IL-20 HT GGA haplotype as the susceptibility loci for both psoriasis and psoriatic arthritis in North Indian population, where patients with this haplotype had increased IL-20 levels." (PMID 31130981, 2019). "Several psoriasis susceptibility loci have been associated with cytokine signaling pathways such as IL-20, IL-17/23 and NF-κB signaling pathways." (PMID 31130981, 2019). "Studies showed that IL-20 expression in humans is associated with chronic inflammation disorders such as psoriasis and rheumatoid arthritis." (PMID 26819710, 2016). "Interleukin 20, a member of the interleukin-10 family of cytokines, is a pro-inflammatory cytokine that is associated with both psoriasis (skin inflammation) and atherosclerosis (a chronic inflammatory disease resulting in lipid deposits)." (PMID 26023727, 2015). "Presence and function of IL-20 has previously been described in other endothelial systems that are linked to local inflammation such as atherosclerosis, psoriasis and rheumatoid arthritis." (PMID 26162095, 2015). "In a case-control study (340 cases and 199 controls), the G allele in rs1713239 (IL20) was associated with psoriasis in a Chinese population." (PMID 24069534, 2013). "In a three-dimensional human epidermis model, IL-22 and IL-20 cause psoriasis-like morphologic changes associated with the inhibition of keratinocyte terminal differentiation and STAT3 upregulation." (PMID 23365685, 2013). "Of note, the haplotype in IL19 and IL20 exhibited a susceptibility factor for the development of psoriasis." (PMID 24069534, 2013). "These cytokines are important in the manifestation of psoriatic lesions and, recently, an association of polymorphisms of IL-20 with psoriasis has been described." (PMID 22792286, 2012). "IL-22, IL-20, IL-26 and IL-18 have all been implicated in inflammatory conditions such as Crohn's disease and Psoriasis in humans." (PMID 20950493, 2010). "These implications are particularly relevant for autoimmune diseases such as psoriasis and rheumatoid arthritis, underscoring the need for further research to elucidate the underlying mechanisms and clinical significance of IL-20 promoter methylation in Tai Chi practitioners." (PMID 41551693, 2025). "IL20RA codes for a receptor for IL20, a cytokine that may be involved in epidermal function and is associated with psoriasis in the Caucasian population." (PMID 39857589, 2024). "The expression of many genes known to be associated with psoriasis, including Lce3f, Sprr2b, Krt15, S100a8, S100a9, Il17a, Il17f, Il18, Il20, Il22, and Ccl20, was downregulated in the skin of IMQ-treated Camk4−/− mice compared with those of IMQ-treated Camk4+/+ mice." (PMID 35869084, 2022). "STAT3 participates in signaling downstream of multiple cytokines implicated in psoriasis, such as IL-6, IL-10, IL-20, IL-22, and IL-23, and may have a role in mediating the innate immune response in psoriatic epidermis." (PMID 32752186, 2020).
psoriasis (continued). "However, it is interesting to note that altered expression of genes including Tpsab1, Shh, S100a7a and Il20, which are associated with tumorigenesis or psoriasis, was observed in the microarray analysis." (PMID 27756876, 2016). "In addition, IL-20 is associated with multiple inflammatory diseases, including psoriasis, rheumatoid arthritis, renal failure, brain injury, and atherosclerosis." (PMID 22962576, 2012). "Finally, there was a significant (p = 0.028) increase in IL-20, a potent inflammatory cytokine that is classically associated with psoriasis and rheumatoid arthritis but has also been shown to promote tumorigenesis through promoting cellular proliferation and migration." (PMID 38831884, 2024). "IL-20 is linked with increased inflammatory activity in RA joints, and its antagonists may offer therapeutic benefits; its overexpression causes psoriasis-like skin conditions, while blocking its pathway reduces psoriasis symptoms." (PMID 39104791, 2024). "Thus, these initial data suggest that IL-20 might serve as a biomarker associated with efficacy in patients with psoriasis." (PMID 23006144, 2012). "These novel DNA aptamers for IL-17 and IL-20 represent valuable tools for studying cytokine biology and developing potential therapeutics for inflammatory and autoimmune conditions like psoriasis and impaired wound healing." (PMID 42017161, 2026). "The significantly elevated levels of IL-20 were identified in patients with psoriasis compared to the control group (p < 0.001)." (PMID 40731810, 2025). "For instance, IL-36 and IL-17C mainly act synergistically to enhance tissue inflammation; overexpression of IL-20 can lead to epidermal changes characteristic of psoriasis; and IL-19 potentiates the effects of IL-17A via a positive feedback mechanism." (PMID 40303401, 2025). "Although studies on serum IL-20 levels are limited, elevated concentrations have been documented both in the lesional skin and in the peripheral blood of patients with psoriasis." (PMID 40731810, 2025). "The administration of IL-20 can change the human epidermis akin to those seen in psoriasis by inhibiting the terminal differentiation of keratinocytes." (PMID 39813538, 2025). "A statistically significant positive correlation was observed between IL-20 concentrations and psoriasis severity, as assessed by the PASI score (p < 0.001)." (PMID 40731810, 2025). "IL-20 is a cytokine belonging to the IL-10 family and its receptor IL-20RB was found to be significantly up-regulated in inflammatory diseases, such as psoriasis and rheumatoid arthritis, indicating its involvement in promoting innate immune responses." (PMID 39519164, 2024). "IL-20 was considered to be involved in the pathogenesis of psoriasis, and a phase I study with an anti-IL-20 monoclonal antibody fletikumab for psoriasis was conducted, however the study was terminated due to lack of efficacy." (PMID 37881433, 2023). "IL-20 belongs to the IL-10 family and is a pro-inflammatory cytokine that plays an essential role in developing inflammatory diseases, such as psoriasis and rheumatoid arthritis." (PMID 38258051, 2023). "A previous study showed that IL-20 controlled T cell infiltration by regulating the expression of MCP-1 in mouse psoriasis models." (PMID 36835229, 2023). "The pro-inflammatory mediators associated with psoriasis are IL1B, IL2, IL6, IL12, IL15, IL17, IL18, and IL20." (PMID 37569685, 2023). "Anti-IL-20 monoclonal antibodies have been evaluated as clinical candidates for the treatment and/or prevention of psoriasis, rheumatoid arthritis, atherosclerosis, osteoporosis, stroke and also bacterial lung infections." (PMID 37887308, 2023). "In chronic inflammatory diseases (e.g., psoriasis, atherosclerosis, and rheumatoid arthritis), IL-20 has been shown to exhibit robust proinflammatory, vascular regenerative, and cell chemotactic effects." (PMID 34122555, 2021).
psoriasis (continued). "Fletikumab, a recombinant human anti–IL-20 mAb, has been tested in two clinical trials, psoriasis and RA." (PMID 32028746, 2020). "Previous studies reported that IL-20 is involved in several inflammatory diseases like psoriasis, rheumatoid arthritis (RA), atherosclerosis, osteoarthritis (OA), and stroke." (PMID 32028746, 2020). "Of note, IL-20 has proinflammatory roles in autoimmune diseases such as, psoriasis and rheumatoid arthritis." (PMID 30755657, 2019). "In conclusion, in contrast to psoriasis where different IL-20 related cytokines play a role, IL-24 is the main IL-20-related cytokine playing a role in PPD-induced CHS, most probably via its effect on keratinocytes." (PMID 30755657, 2019). "Clinical trials that investigate inhibitors of IL-20 (fletikumab) and IL-22 (fezakinumab) in psoriasis and RA have been terminated." (PMID 30319661, 2018). "IL-20 can promote hyper proliferation, and aberrant keratinocytes differentiation, which are the distinctive characteristics of psoriasis." (PMID 30326614, 2018). "IL-20 is emerging as a potent angiogenic, chemotactic, and proinflammatory cytokine related to several chronic inflammatory disorders likes psoriasis, atherosclerosis, cancer, liver fibrosis, and RA." (PMID 29690863, 2018). "Previous studies indicated that IL-20 has a close connection with psoriasis, atherosclerosis, and stroke." (PMID 29690863, 2018). "Polymorphism in the genes coding for IL-19, IL-20 and LTA (lymphotoxin alpha) have been associated with both PPP and psoriasis." (PMID 27152848, 2016). "In psoriasis, epidermal keratinocytes are a major source of IL-20 synthesis and the transcriptional level of IL-20 is strongly upregulated in psoriatic skin lesions." (PMID 26819710, 2016). "Overexpression of Il20, Il22 or Il24 in mice leads to the development of psoriasis-like skin lesions, and levels of IL-19, IL-20, IL-22 and IL-24 are increased in psoriatic skin." (PMID 27799070, 2016). "Very interestingly, two recent clinical trials have demonstrated that anti-IL-20 monoclonal antibody is effective in the treatment of RA and psoriasis." (PMID 27799070, 2016). "IL-20 concentration was positively correlated to psoriasis severity expressed by PASI (r = 0.418; p = 0.001), BSA (r = 0.579; p < 0.001), and PGA (r = 0.392; p = 0.002)." (PMID 26146462, 2015). "Over-activity of IL-20 has been demonstrated in inflammatory conditions of the skin like psoriasis and rheumatoid arthritis." (PMID 26162095, 2015). "IL-20 is also highly expressed after infection with SL1344, and this IL is associated with epidermal function and psoriasis; however, its role in intestinal infection is undetermined." (PMID 25964470, 2015). "The importance of IL-20 in psoriasis is further supported by the observation that a specific single nucleotide polymorphism in the promoter region of the IL-20 gene was associated with psoriasis progression." (PMID 26252485, 2015). "Other cytokines and chemokines associated with psoriasis include IL19, IL20, IL15, and MCP1 (monocyte chemoattractant protein)." (PMID 24069534, 2013). "IL-24 expression is increased in inflammatory skin disease like AD or psoriasis and IL-24 induces, as well as the other IL-10 family members IL-19 and IL-20, the proliferation of keratinocytes in 2D cultures." (PMID 23531535, 2013). "Like IL19, the expression of the IL20 gene is also increased in inflammatory skin diseases like AD or psoriasis and IL20 mRNA is upregulated in lesional compared to non-lesional psoriatic skin." (PMID 23531535, 2013). "In some respects, the strongest evidence from our study supports the IL-20 family cytokines as drivers of differential gene expression in psoriasis (i.e., IL-19, IL-20 and IL-24)." (PMID 23915137, 2013). "Here, we extend the findings for the skin of patients with psoriasis and demonstrate for the first time the effects of alefacept treatment on IL-20 expression in the synovium of patients with PsA." (PMID 23006144, 2012).
psoriasis (continued). "This study is the first to investigate the effects of alefacept treatment on IL-20 expression in paired synovial tissue and psoriatic lesional skin of patients with both PsA and psoriasis." (PMID 23006144, 2012). "High IL-20 mRNA level is found in the skin of patients with psoriasis and the protein level is high in synovial fluid from patients with rheumatoid arthritis." (PMID 23094074, 2012). "We have previously shown that inflammatory DCs are important pathogenic cells in psoriasis, as they produce TNF, iNOS, IL-20, and IL-23, and are TRAIL+." (PMID 22348003, 2012). "IL-20 expression in lesional skin of PsA patients decreased significantly (P = 0.04) 6 weeks after treatment and correlated positively with the Psoriasis Area and Severity Index (PASI)." (PMID 23006144, 2012). "Recent reports have shown that IL-20 functions as a proinflammatory cytokine in several inflammatory diseases, of which psoriasis has been the most extensively studied." (PMID 23006144, 2012). "The results presented here show that IL-20 is expressed in psoriatic skin lesions and synovial tissue from patients with both psoriasis and PsA." (PMID 23006144, 2012). "As a recent example of this, findings in a xenotransplantation mouse model suggest that blockage of IL-20 signaling by systemic administration of anti-IL20 antibodies leads to resolution of psoriasis." (PMID 20594301, 2010). "In accordance, the expression of several cytokines assumed to play a role in the pathogenesis of psoriasis (i.e. IL-20, TNF, IL-8, and IL-6) are p38 MAPK-regulated." (PMID 20072629, 2010). "Notably, IL-19 and IL-20 are overexpressed in the basal and suprabasal layers of psoriatic keratinocytes, although their circulating levels in the serum of psoriasis patients are reduced when compared to healthy controls." (PMID 40731810, 2025). "Moreover, IL-17A principally drives the expression of four key cytokines: IL-36, IL-17C, IL-20, and IL-19, each possessing distinct functions in psoriasis." (PMID 40303401, 2025). "Dysfunctional regulation of IL-20 cytokines could lead to uncontrollable wound healing in psoriasis which could be a contributing factor to the pathogenesis of this disease, although their role in airway mucosa was unknown." (PMID 37887308, 2023). "Indeed, previous studies have demonstrated that IL-20 cytokines and their receptors were overexpressed in keratinocytes of the lesional skin of psoriasis and spongiotic dermatitis." (PMID 37887308, 2023). "Not much is known about the function of the IL-19, IL-20, and IL-24 cytokines and their receptors, which are intrinsic to keratinocytes and are mostly associated with autoimmunity in psoriasis." (PMID 36225230, 2022). "Furthermore, DMF inhibited NF-κB and downregulated NF-κB-dependent mediators in psoriasis-relevant cells, i.e., IL-8 and IL-20 in keratinocytes and intercellular adhesion molecule in dermal fibroblasts." (PMID 34440900, 2021). "Interleukin-20 (IL-20) is involved in psoriasis, atherosclerosis, and rheumatoid arthritis." (PMID 31947928, 2020). "Elevated expression of IL-20 in transgenic mice produced skin abnormalities similar to psoriasis." (PMID 29538330, 2018). "The IL-20 cytokines IL-19, IL-20, IL-22, IL-24, and IL-26 are elevated in autoimmune/inflammatory diseases, such as in the skin of patients with psoriasis, in synovial fibroblasts, and macrophages of patients with rheumatoid arthritis and in patients with inflammatory bowel disease." (PMID 29967613, 2018). "In line with this, single-nucleotide polymorphisms of the IL-19 gene (but not the IL-20 or IL-24 genes) are protective in psoriasis." (PMID 30319661, 2018). "Furthermore, the over expression of IL-20 in transgenic mice generated psoriasis-like skin lesions and treatment of human skin xenografts with IL-20 induced psoriasis-like skin lesions." (PMID 26819710, 2016). "Our findings may propose an aberrant influence of IL-20 in the case of the high concentrations as often found in psoriasis." (PMID 26819710, 2016).